B4GAT1 (beta-1,4-glucuronyltransferase 1)
Description:
Beta-1,4-glucuronyltransferase involved in O-mannosylation of alpha-dystroglycan (DAG1). Transfers a glucuronic acid (GlcA) residue onto a xylose (Xyl) acceptor to produce the glucuronyl-beta-1,4-xylose-beta disaccharide primer, which is further elongated by LARGE1, during synthesis of phosphorylated O-mannosyl glycan. Phosphorylated O-mannosyl glycan is a carbohydrate structure present in alpha-dystroglycan (DAG1), which is required for binding laminin G-like domain-containing extracellular proteins with high affinity. Required for axon guidance; via its function in O-mannosylation of alpha-dystroglycan (DAG1) (By similarity).
Synonyms: iGnT; B3GNT1; B3GNT6; iGAT; BETA3GNTI; B3GN-T1; MDDGA13
Tractability: Antibody: UniProt predicts a signal peptide or a membrane-spanning region. PROTAC: ubiquitination databases record sites on it; its protein half-life has been measured.
Gene: Protein-coding gene on chromosome 11 (66,345,374 to 66,347,638, reverse strand). Ensembl gene ENSG00000174684.
Subcellular location: Golgi apparatus membrane
Pathways (Reactome):
Disease: Defective LARGE causes MDDGA6 and MDDGB6
Metabolism: Keratan sulfate biosynthesis
Metabolism of proteins: Matriglycan biosynthesis on DAG1
Gene Ontology:
Molecular function: glucuronosyltransferase activity; N-acetyllactosaminide beta-1,3-N-acetylglucosaminyltransferase activity; protein binding
Biological process: poly-N-acetyllactosamine biosynthetic process; protein O-linked glycosylation via mannose; keratan sulfate proteoglycan biosynthetic process; glycoprotein biosynthetic process
Cellular component: extracellular exosome; Golgi apparatus; Golgi membrane
Genetic constraint (gnomAD): Loss-of-function variants: 18 observed, 29.72 expected, observed/expected ratio (o/e) 0.61, 90% interval 0.42 to 0.9. The upper end of that interval is the gene's LOEUF score, 0.9, which puts it in group 3 of 6, group 1 being the genes least tolerant of losing a copy. Missense variants: 458 observed, 513.1 expected, observed/expected ratio (o/e) 0.89, 90% interval 0.83 to 0.96. Synonymous variants: 217 observed, 220.27 expected, observed/expected ratio (o/e) 0.99, 90% interval 0.88 to 1.1.
Gene-disease validity (ClinGen):
ClinGen rates the evidence that B4GAT1 causes each of these diseases.
muscular dystrophy-dystroglycanopathy (congenital with brain and eye anomalies), type A13 (autosomal recessive): Moderate.
Homologues: Orthologues: chimpanzee B4GAT1 (100% identical), macaque B4GAT1 (99% identical), rabbit B4GAT1 (98% identical), dog B4GAT1 (98% identical), pig B4GAT1 (98% identical), guinea pig B4GAT1 (97% identical), mouse B4gat1 (97% identical), rat B4gat1 (96% identical), tropical clawed frog b4gat1 (53% identical), zebrafish b4gat1 (52% identical), Caenorhabditis elegans bgnt-1.1 (18% identical), Drosophila melanogaster CG11149 (17% identical), and 2 more. Paralogues in human: LARGE1 (25% identical), LARGE2 (25% identical), GXYLT2 (9% identical), GXYLT1 (8% identical), XXYLT1 (5% identical).
Diseases named in the same sentence as B4GAT1 in open-access papers:
B4GAT1 is named in the same sentence as 14 diseases in open-access papers, as found by Europe PMC text mining. Sharing a sentence is not in itself a finding about the gene and the disease. The quoted sentences say what the papers report.
dystroglycanopathies (4 papers, 2014 to 2024). "To model mild forms of dystroglycanopathy, we examined mice expressing missense mutations in B4gat1 (β–1,4-glucuronyltransferase, B4gat1M155T) and Fkrp (fukutin related protein, FkrpP448L), two genes required for Dystroglycan glycosylation." (PMID 38179984, 2024). "However, an ENU-based genetic screen for abnormal CNS axonal tracks identified a viable B4gat1(B3gnt1) dystroglycanopathy mouse model carrying a p.M155T B4gat1 mutation." (PMID 25279699, 2014).
prostate carcinoma (3 papers, 2014 to 2022). A carcinoma that arises from epithelial cells of the prostate gland. "The loss of B4GAT1 expression and laminin-binding by α-DG in these cells was inversely correlated with the observed malignancy and tumor progression of the prostate cancer when these cells were transplanted into SCID mice." (PMID 25279699, 2014). "The mRNA levels of the B4GAT1 gene have been found to be decreased or undetectable in cell lines derived from prostate cancer, including PC3, PC3-L and LNCaP, and from breast cancer, such as MDA-MB-231 and MDA-MB-435." (PMID 36494657, 2022). "This could be attributed to the downregulation of B4GAT1 and LARGE1 genes existing in prostate cancer cell lines, as it was also the case for breast cancer cell lines." (PMID 36494657, 2022). "Similarly, it was demonstrated that expression of B4GAT1 (B3GNT1) is absent in a IIH6-negative subpopulation (PC3-L) of an otherwise IIH6-positive human prostate cancer cell line (PC3)." (PMID 25279699, 2014).
Walker-Warburg syndrome (3 papers, 2014 to 2018). "A truncating mutation in B4GAT1 is known to causes severe Walker-Warburg syndrome, a congenital muscular dystrophy." (PMID 30220890, 2018). "The role of BGNT-1.1 in this process, seemingly independent of dystroglycan, supports the notion that B3GNT1/B4GAT1-associated Walker-Warburg syndrome may result at least in part from ciliary dysfunction, and thus could be considered a novel ciliopathy." (PMID 27508411, 2016). "Similar to their counterparts in other dystroglycanopathy genes, B4GAT1(B3GNT1) loss-of-function mutations in human patients result in Walker-Warburg Syndrome (WWS), the most severe condition in a range of clinically defined CMDs that are accompanied by brain and eye malformations." (PMID 25279699, 2014).
Aqueductal stenosis (1 paper, 2024). Stenosis of the cerebral aqueduct (also known as the mesencephalic duct, aqueductus mesencephali, or aqueduct of Sylvius), which connects the third cerebral ventricle in the diencephalon to the fourth ventricle, which is between the pons and cerebellum. "Moreover, our study identifies the downregulation of specific genes, such as L1CAM, PCDH9, ISLR2, ADAMTSL2, and B4GAT1, which have been previously well characterized as playing an important role in congenital hydrocephalus and aqueductal stenosis." (PMID 39118132, 2024).
congenital hydrocephalus (1 paper, 2024). Hydrocephalus that is present at birth. "Moreover, downregulation of multiple proteins associated with congenital hydrocephalus (e.g., L1CAM, PCDH9, ISLR2, ADAMTSL2, and B4GAT1) points to a possible shared molecular foundation between congenital hydrocephalus and iNPH." (PMID 39118132, 2024).
leukemia (1 paper, 2022). A malignant (clonal) hematologic disorder, involving hematopoietic stem cells and characterized by the presence of primitive or atypical myeloid or lymphoid cells in the bone marrow and the blood. "Furthemore, in solid tumors and derived cell lines (i.e., leaving aside leukemia) genes directly involved in the synthesis of core M3 glycan and matriglycan, such as POMGNT2, CRPPA, B4GAT1, LARGE1 and LARGE2 and/or their encoded proteins, are found downregulated." (PMID 36494657, 2022).
limb-girdle muscular dystrophy (1 paper, 2014). Limb-girdle muscular dystrophy (LGMD) is a heterogeneous group of muscular dystrophies characterized by proximal weakness affecting the pelvic and shoulder girdles. "Milder B4GAT1 mutations with residual enzyme activity are expected to cause a milder Limb Girdle Muscular Dystrophy (LGMD) phenotype, but patients with such mutations have not yet been described." (PMID 25279699, 2014).
muscular dystrophies (1 paper, 2014). "Understanding the role of B4GAT1 and other glycosyltransferases that build functionally glycosylated dystroglycan could help to develop treatments for diseases such as muscular dystrophies." (PMID 25279697, 2014).
pancreatic ductal adenocarcinoma (1 paper, 2022). An infiltrating adenocarcinoma that arises from the epithelial cells of the pancreas. "The B4GAT1 gene (formerly B3GNT1) has been detected underexpressed at the mRNA level in pancreatic ductal adenocarcinoma, this being associated with a poor patient prognosis." (PMID 36494657, 2022).
tumor (7 papers, 2014 to 2025). "In addition, depletion of matriglycans by lowering the expression of B4GAT1 promotes cell migration and thereby increases tumor formation." (PMID 35743105, 2022). "There were 253 genes (13.6%) that had decreased expression shared across tumor types, including NPTXR, SCG2, B4GAT1, and ATRN." (PMID 36909536, 2023).
cancer (3 papers, 2014 to 2025). A tumor composed of atypical neoplastic, often pleomorphic cells that invade other tissues. "Since overexpression of LARGE significantly inhibits the cancer cell migration ability and low expression of B4GAT1 results in increased cancer cell invasion, altered glycosylation of α-DG is considered to be associated with cancer development and progression." (PMID 35743105, 2022). "Further, our results likely clarify how loss of expression of B4GAT1 (B3GNT1), similar to loss of expression of LARGE, can lead to loss of laminin-binding α-dystroglycan and promote metastasis in certain cancers." (PMID 25279697, 2014). "Similarly, emerging evidence implicates dysregulation and decreased expression of RhoGAPs (ARHGAP1), B4GAT1, and FGA in various malignancies, including cancer." (PMID 39819313, 2025).
B4GAT1 also shares sentences with these, for which no sentence is quoted: breast carcinoma (1 paper); ciliopathy (1); congenital muscular dystrophy (1).